LGR5 (leucine rich repeat containing G protein-coupled receptor 5)
Diseases named in the same sentence as LGR5 in open-access papers (continued):
Sharing a sentence is not in itself a finding about the gene and the disease.
intestinal cancer (continued). "Moreover, LGR5 that is overexpressed in human CRCs is a Tcf4 target gene and LGR5 was then used to identify crypt SCs as the cells-of-origin of intestinal cancer." (PMID 24224156, 2013). "Notably, using Lgr5–CreER to delete Apc within ISCs led to rapid formation of intestinal adenomas, strongly suggesting that LGR5+ ISCs might be the cells of origin for intestinal cancer." (PMID 26414675, 2016). "In the article titled “Crypt stem cells as the cells-of-origin of intestinal cancer,” which was the fifth co-cited paper, Clevers, H investigated the role of APC in the development of intestinal cancer using an LGR5 knock-in mouse model." (PMID 41194856, 2025). "The characterization of Lgr5+ crypt-based columnar (CBC) cells, that include the intestinal stem cells (ISCs) shown to act as cells-of-origin of intestinal cancer, attests to the value of these models." (PMID 32948837, 2020). "It remains to be elucidated whether a comparable hierarchical relationship between LGR5+ cells and CLU+ cells is conserved in human intestinal cancer tissues." (PMID 31906589, 2020). "We crossed Ubc9+/− mice with mice harboring a conditional ablation of Apc either all along the crypt–villus axis or only in Lgr5+ crypt-based columnar (CBC) cells, the cell compartment that includes the intestinal stem cells proposed as cells-of-origin of intestinal cancer." (PMID 32948837, 2020). "Furthermore, OPCs downregulated several well-established large intestinal cancer stem cell markers such as CD133, CD44 and LGR5, indicating that OPCs particularly target cancer stem cells in CRC." (PMID 29463813, 2018). "However the most selective and promising marker of the stem cell in intestinal epithelium and of the intestinal cancer stem cells is LGR5 (UNIPROT Accession # O75473; UNIGENE # Hs.658889; also called GPR49)." (PMID 21829496, 2011).
colorectal tumors (26 papers, 2011 to 2024). "Importantly, the expression of a stem cell signature, that included Lgr5 and EphB2, was associated with more aggressive colorectal tumors and predicted disease relapse." (PMID 32231042, 2020). "A RevSC signature, that includes CLU, has been confirmed in human colorectal tumours and, similarly to what has been observed in the mouse intestine, it appears to be largely mutually exclusive with the LGR5+ve stem cell signature." (PMID 38319453, 2024). "In mouse models, conditioned knockout of APC in Lgr5− cells inhibited the growth of intestinal adenomas, while conditional knockout of APC in Lgr5+ cells drove intestinal adenomas, proving that Lgr5+ cells are CSCs for colorectal tumors." (PMID 38254219, 2024). "Shimokawa and colleagues traced LGR5+ colon stem cells in patient-derived colorectal tumor organoids xenografted to mice by knocking in a conditional Cre recombinase into the LGR5 locus and labeling the organoids with a multi-color rainbow reporter." (PMID 36358834, 2022). "Genetic ablation of Lgr5+ stem cells in colorectal tumors of transgenic mice indicated a critical role for Lgr5+ cells in the establishment and maintenance of CRC-derived liver metastasis." (PMID 32231042, 2020). "In recent years, several reports revealed that LGR-5 overexpression was observed in various tumors, such as colorectal tumors, ovarian tumors, basal cell carcinoma, and esophageal adenocarcinoma." (PMID 31126119, 2019). "The function of LGR5/GPR49 in tumorigenesis is supported by its ability to induce transformation of NIH3T3 cells in the presence of conditioned media from colorectal tumor cells." (PMID 21978106, 2011). "Conversely, the LGR5+ve CSC signature was predominantly found in conventional colorectal tumours." (PMID 38319453, 2024). "Accordingly, a meta-analysis study showed that higher expression of the CSC biomarker LGR5 was associated with poor prognosis in CRC patients, supporting the need for a better understanding of the biological characteristics of different colorectal tumours required to guide therapeutic decisions." (PMID 38339195, 2024). "Moreover, RSPO2 was shown to inhibit the growth of colorectal tumors through LGR5-dependent WNT signaling." (PMID 33807916, 2021). "Targeting BCL-3 may be an effective mechanism to prevent the reversion of LGR5+ cells in colorectal tumours." (PMID 30792270, 2019). "LGR5 is overexpressed in primary colorectal tumours: overexpression could conceivably be due to enrichment of ‘stem-like’ cells, to upregulation of the wnt signalling pathway, and/or to wnt pathway-dependent maintenance of ‘stemness”." (PMID 21829496, 2011). "The re-emergence of LGR5 expression in metastatic cell lines has perhaps recently been explained by de Sousa and colleagues, where LGR5+ cells were dispensable for an already established colorectal tumour, but were required for re-establishment (and survival) of the tumour at a distant site." (PMID 29149105, 2018).
colorectal tumors (continued). "In addition, promoter hypermethylation and loss of function mutations in LGR5 and LGR6 have been discovered in some colorectal tumor samples, again suggesting that these genes could act as tumor suppressors in some contexts." (PMID 23596566, 2013). "Expression of ERBB3 and intestinal stem cell markers (LGR5, EPHB2, CD44s and CD44v6) was assessed by qRT-PCR in primary colorectal tumours (stages 0 to IV) and matched normal tissues from 53 patients." (PMID 26367378, 2015). "These organoids are derived from the LGR5+ (leucine-rich repeat-containing G-protein coupled receptor 5) stem cell population of colonic crypts within adjacent normal tissue collected during the resection of colorectal tumors." (PMID 36018850, 2022). "Among primary colorectal tumors, 40% (67/169) were positive for lgr5 methylation, while none of the normal colon tissues were positive for lgr5 methylation." (PMID 26599100, 2015). "Furthermore, studies have reported the RSPO2-induced, Lgr5-dependent Wnt signaling-negative feedback loop, exhibiting a tumor-suppressive activity in colorectal tumors." (PMID 31358061, 2019).
cervical carcinoma (23 papers, 2014 to 2025). A carcinoma arising from either the exocervical squamous epithelium or the endocervical glandular epithelium. "Breast and cervical cancer studies reported that high LGR5 expression was associated with chemotherapy resistance." (PMID 39821694, 2025). "Our findings also support a growing body of literature associating LGR5 with aggressiveness in other cancer subtypes including: colorectal, gastric, and cervical cancers, as well as malignant glioma." (PMID 26416247, 2015). "All these results demonstrate that LGR5 expression is positively associated with the activity and expression of key molecules of the Wnt/β-catenin pathway in cervical cancer cells." (PMID 25193857, 2014). "In the present study, we show, for the first time, the cytotoxicity of disulfiram may be superior to cisplatin caused by targeting LGR5-positive cervical cancer stem-like cells in cervical cancer." (PMID 35534815, 2022). "In addition, we found that Wnt signaling was involved in the LGR5-associated cancer stemness in cervical cancer cells." (PMID 28880275, 2017). "This might be explained by our study, which showed that LGR5 promotes tumor progression by increasing the number of CSCs in the cervical cancer cell population that are associated with increased cell migration, cell invasion and chemoresistance capability." (PMID 28880275, 2017). "LGR5 protein expression was positively correlated with cervical cancer proliferation in vitro and in vivo." (PMID 39821694, 2025). "A cervical cancer study found that LGR5 promoted CSCs traits and chemo-resistance through the WNT/β-catenin signaling pathway." (PMID 39821694, 2025). "We tested the effects of DSF/Cu complex and DDP on cervical cancer cells with different expression levels of LGR5." (PMID 35534815, 2022). "Our previous studies indicated LGR5 promotes cancer stem cell traits and chemoresistance in cervical cancer cells." (PMID 35534815, 2022). "Our previous studies manifested that overexpression of LGR5 promotes cervical cancer cell stemness and chemoresistance." (PMID 35534815, 2022). "When Lgr5 is overexpressed in cervical cancer cells, there are increases in the tumorigenicity of the cells when grafted onto mice." (PMID 36016373, 2022). "Taken together, these results indicate that the disulfiram/copper complex is toxic in cervical cancer cell lines in vitro and in vivo by mechanisms including targeting LGR5+ cancer stem-like cells." (PMID 35534815, 2022). "The progression and tumorigenesis of cervical cancer cells occur through the activation of a G protein receptor family member, called LGR5, gradually expressed in cervical cancer cells, leading to Wnt pathway activation." (PMID 37305016, 2022). "In other words, DSF/Cu treatment was superior to cisplatin by its ability of eliminating the stem cell-like LGR5 + cells pool in cervical cancer." (PMID 35534815, 2022). "The possible mechanism is that LGR5 recruits the LRP-FZD receptor complex and reinforces Wnt signaling following the phosphorylation of LRP, ultimately induces LGR5-mediated promotion of cervical cancer growth via the Wnt/β-catenin signaling pathway." (PMID 32758292, 2020). "Leucine-rich repeats containing G protein-coupled receptors 5 (LGR5) was also found to regulate β-catenin in human cervical cancer indirectly." (PMID 32758292, 2020). "The inhibitory effect of FOXF2 on β-catenin, c-Myc, CyclinDl, MMP9, and Lgr5 will provide an important theoretical basis for the diagnosis and targetted therapy of cervical cancer." (PMID 30249755, 2018). "Taken together, these data demonstrate that the LGR5-positive cells from LGR5-overexpressing cervical cancer cells have the ability to differentiate both in vitro and in vivo." (PMID 28880275, 2017). "Our previous study showed that LGR5 functions as a tumor promoter in cervical cancer by activating the Wnt/β-catenin pathway." (PMID 28880275, 2017).
cervical carcinoma (continued). "Our data indicated that LGR5 has a vital oncogenic role through promoting CSC traits in cervical cancer." (PMID 28880275, 2017). "Taken together, these results suggested that the Wnt/β-catenin pathway is involved in the promotion of cervical cancer cell stemness by LGR5." (PMID 28880275, 2017). "Here, we have modulated the expression of LGR5 using an overexpression vector or short hairpin RNA in cervical cancer cell lines." (PMID 28880275, 2017). "25, 26, 27, 28 These results indicated that LGR5 positively modulates the expression of stem cell markers and stem-like properties in cervical cancer." (PMID 28880275, 2017). "In summary, our comprehensive functional analysis of LGR5 in cervical cancer cell lines conclusively links LGR5 expression to cervical CSCs." (PMID 28880275, 2017). "The results indicated that a subpopulation of human cervical cancer cells with elevated LGR5 expression possesses enhanced self-renewal capacity, differentiation potential and tumorigenicity." (PMID 28880275, 2017). "In summary, our data presented here highlights LGR5 as a candidate oncoprotein mediating key signalling pathways in NB and possibly other cancers, such as breast and cervical cancer, and glioblastoma." (PMID 26517508, 2015). "Taken together, these results demonstrate that the LGR5-mediated promotion of cervical cancer cell proliferation is mediated by the Wnt/β-catenin pathway." (PMID 25193857, 2014). "Collectively, these results suggest that LGR5 promotes the tumor growth of cervical cancer cells, possibly by accelerating the cell cycle." (PMID 25193857, 2014). "We found that LGR5 expression was positively correlated with β-catenin, cyclinD1, and c-myc expression in randomly selected cervical cancer sections." (PMID 25193857, 2014). "Taken together, these results demonstrate that LGR5 can promote proliferation and tumor formation in cervical cancer cells by activating the Wnt/β-catenin pathway." (PMID 25193857, 2014). "In this study, the expression of LGR5 gradually increases from normal cervix to cervical cancer in situ and to cervical cancers as revealed by immunohistochemistry and western blot analyses." (PMID 25193857, 2014). "LGR5 expression in cervical cancer was approximately twofold greater than that in normal cervix (p<0.05)." (PMID 25193857, 2014). "Nude mice were injected subcutaneously with these LGR5-modulated cervical cancer cells, and the growth of tumors was monitored in terms of tumor volume every three days." (PMID 25193857, 2014). "All these data suggest that LGR5 most likely enhances the tumor progression of cervical cancer cells by promoting cell proliferation." (PMID 25193857, 2014). "The positive LGR5 expression rates were 17% (5/30) in normal cervix, 65% (11/17) in cancer in situ, and 84% (54/64) in cervical cancers (p<0.01)." (PMID 25193857, 2014). "Accordingly, analysis of the IRS of LGR5 also revealed that LGR5 expression is significantly increased from normal cervix to cervical cancer in situ and finally to cervical cancers (p<0.01)." (PMID 25193857, 2014). "Subsequently, through shRNA knockdown or stable plasmid transfection, the LGR5 protein level was found to be positively related to the proliferation of cervical cancer cells." (PMID 25193857, 2014). "All these results indicate that LGR5 expression is positively related to the activity of the Wnt/β-catenin pathway in cervical cancer cells." (PMID 25193857, 2014). "In summary, our study demonstrates that LGR5 promotes cell proliferation and tumor formation in cervical cancer cells by activating the Wnt/β-catenin pathway." (PMID 25193857, 2014). "All of our findings together indicate that LGR5 functions to promote the development and progression of cervical cancer, consistent with previous reports in basal cell carcinoma and malignant glioma." (PMID 25193857, 2014).
cervical carcinoma (continued). "All these results suggest that the LGR5-promoted proliferation and tumor formation of cervical cancer cells in vivo is possibly mediated by potentiating the Wnt/β-catenin pathway." (PMID 25193857, 2014). "In addition, our previous studies demonstrated that LGR5 promotes cancer stem cell traits and chemoresistance in cervical cancer." (PMID 35534815, 2022). "To determine whether DSF/Cu can inhibit LGR5-positive cervical cancer stem-like cells in vivo, we used a xenograft model of modified LGR5-positive/negative SiHa and HeLa cells in BALB/c mice." (PMID 35534815, 2022). "Our previous studies have demonstrated that high aldehyde dehydrogenase (ALDH) activity may represent a functional marker for cervical CSCs and LGR5 can promote cervical cancer stem cell traits and chemoresistance." (PMID 35534815, 2022). "Our findings indicate that the cytotoxicity of DSF/Cu complex may be superior to cisplatin because of targeting LGR5-positive cervical cancer stem-like cells in cervical cancer." (PMID 35534815, 2022). "Furthermore, other studies have determined that the presence of LGR5 in cervical cancer is indicative of enhanced self-renewal capacity, differentiation, and tumorigenicity." (PMID 32256979, 2020). "Interestingly, LGR-5 appears to not only be a bona fide marker, but also a tumor promoter in cervical cancer via the Wnt/β-catenin pathway." (PMID 31126119, 2019). "LGR5 has been reported to accelerate proliferation in several cell lines, including skin basal carcinoma cells, corneal endothelial cells, brain cancer stem-like cells and cervical cancer cells." (PMID 29601474, 2018). "Based on this study, LGR5 may be used as a potential therapeutic target for the treatment of cervical carcinoma." (PMID 28880275, 2017). "In the other word, modified LGR5+ cells are indeed CSCs in cervical cancer." (PMID 28880275, 2017). "LGR5+ cervical cancer cells exhibited highly tumorigenic capacity in vivo." (PMID 28880275, 2017). "The results indicate that elevated LGR5 expression could enhance the resistance of cervical cancer cells to a constant concentration of cisplatin for a certain period of time." (PMID 28880275, 2017). "Moreover, Lgr5-promoted proliferation and tumor progression of cervical cancer cells in vivo is possibly mediated by Wnt/β-catenin pathway." (PMID 28404917, 2017). "We demonstrated that elevated LGR5 expression in cervical cancer cells increased tumorsphere-forming efficiency; conferred chemoresistance to cisplatin treatment; augmented cell migration, invasion and clonogenicity; and elevated the levels of stem cell-related transcription factors in vitro." (PMID 28880275, 2017). "Moreover, immunostaining assays revealed that the tumor tissues formed by LGR5-overexpressing cells had much stronger Ki67 expression, suggesting that LGR5 promoted the tumor formation of cervical cancer cells by accelerating cell proliferation." (PMID 25193857, 2014). "Furthermore, the LGR5 protein was found to be highly expressed in the cytoplasm of all cervical cancer cell lines (HeLa, SiHa, C33A, and Caski) by immunohistochemistry and western blot assay." (PMID 25193857, 2014). "In the present study, blockage with DKK-1, an inhibitor of Wnt/β-catenin signaling, resulted in a significant inhibition of the cervical cancer cell proliferation induced by LGR5, suggesting that LGR5 promotes cervical cancer cell proliferation via activation of the Wnt/β-catenin pathway." (PMID 25193857, 2014). "In addition, an analysis of the GSE5787 microarray datasets for 82 cervical cancer patients also showed that LGR5 expression had a significant correlation with the expression of these proteins." (PMID 25193857, 2014). "Furthermore, DSF/Cu could also reduce the cancer stem cell-like LGR5+ cells which lead to cisplatin resistance in cervical cancer cells." (PMID 35534815, 2022).